CAT (catalase)
Diseases named in the same sentence as CAT in open-access papers (continued):
Sharing a sentence is not in itself a finding about the gene and the disease.
breast carcinoma (continued). "Since the activity and expression of catalase are significantly altered in osteosarcoma and breast cancer cells, we enthusiastically encourage the proposal that ATO should be administered in combination with pro-oxidant drugs." (PMID 29467594, 2018). "MCF-7 breast cancer cells chronically exposed to ascorbate/menadione became resistant (Resox cells) by increasing mainly catalase activity." (PMID 29535798, 2018). "In line with our previous report, chromatin remodeling appears as the main regulator of catalase expression in breast cancer after chronic exposure to an oxidative stress." (PMID 29535798, 2018). "Taking together, these findings and previous results obtained in our laboratory suggest that chromatin remodelling is a major regulatory process controlling catalase expression in breast cancer cells during resistance acquisition against an oxidative stress." (PMID 29535798, 2018). "Taking together, these results show that ATO sensitizes breast cancer cells by modulating ROS formation and transcriptional activity of catalase promoter." (PMID 29467594, 2018). "Our investigation into a reengineered catalase biologic offers new molecular insight for breast cancer." (PMID 28281569, 2017). "On the other hand, overexpression of Cu/ZnSOD, MnSOD and catalase lowered both the growth rate as well as the aggressive nature of breast cancer cells." (PMID 27391159, 2016). "At last, we performed experiments on colorectal and breast cancer cells, various cellular models of neurodegenerative diseases and colitis to examine if the formation CAT–Fe(III) sulfheme takes place under pathological conditions." (PMID 27848965, 2016). "This strongly suggests that superoxide anion radicals also participate in the inactivation of CAT activity, in agreement with O2·− contribution to the inactivation of CAT bioactivity in human breast cancer (HBC) cells." (PMID 27848965, 2016). "In fact, a decreased catalase activity has been found both in blood samples and in tissues of breast cancer patients and in oral and pancreatic carcinomas." (PMID 27418953, 2016). "Non-surgical BCT can be performed using KORTUC II, which has three major characteristics: imaging guidance by ultrasonography; enzyme-targeting of peroxidase/catalase; and targeting of breast cancer stem cells via the CD44 receptor." (PMID 26593948, 2015). "Patients with breast cancer in chemotherapy with epirubicin (90 mg/m2) and cyclophosphamide (600 mg/m2) also showed reduced CAT, SOD, GSH, and GPx activity and increased TBARS levels." (PMID 26576218, 2015). "In contrast, ascorbic acid resistant cancer cell lines, for example the breast carcinoma cell line BT-20, exhibited increased catalase protein and enzymatic activity." (PMID 22551313, 2012). "In vitroγ-irradiation of blood of breast cancer patients with doses of 2 Gy and 9 Gy showed increased expression of MnSOD and CAT, and unchanged expression of CuZnSOD in leukocytes." (PMID 22645500, 2012). "For example, paclitaxel, an inhibitor of microtubule dynamics and mitosis, induces a marked increase in catalase-inhibitable oxidation of the redox-sensitive probe H2DCFDA in breast cancer cell lines." (PMID 22848499, 2012). "Expression of catalase was silenced by catalase-specific short hairpin RNA (sh-RNA) in BT-20 breast carcinoma cells." (PMID 22551313, 2012). "Transgenic mice expressing a human catalase gene (mCAT) were crossed with MMTV-PyMT transgenic mice that develop metastatic breast cancer." (PMID 21605372, 2011). "Levels and activities of superoxide dismutase (SOD), catalase (CAT) and glutathione peroxidase (GPx) in liver, kidney and breast were reduced by 50 to 80% in mice with induced breast cancer, but were re-established to normal by the combination treatment." (PMID 18946424, 2008). "The mitochondrial antioxidant enzyme, SOD2, was over-expressed in HCC1937 cells, whereas catalase was expressed at wild type level in both breast cancer cell lines." (PMID 17192190, 2006).
breast carcinoma (continued). "We have shown a decrease in salivary catalase activity in all cases before breast cancer surgery, which may indicate a decrease in its production by the oral microbiota and a decrease in its intake from the plasma." (PMID 41596237, 2026). "In patients with breast cancer and fibroadenomas, the catalase activity statistically significantly decreased (p = 0.0001), but SOD (p = 0.0270) and GGT (p = 0.0000) activity increased, and the NO (p = 0.0000) and MDA (p = 0.0007) levels increased compared with the healthy control." (PMID 40429927, 2025). "Among the group of biochemical parameters, catalase activity was most significantly reduced in the luminal breast cancer subtypes: luminal A (−19.2%, p = 0.0201), luminal B(−) (−24.0%, p = 0.0036), and luminal B(+) (−34.9%, p = 0.0130) compared with the healthy controls." (PMID 40429927, 2025). "Superoxide dismutase and catalase mimetic-drugs MnTmPyP and 134 have distinct impacts on breast cancer cell proliferation via TNFa-induced NF-B regulations confirm our findings that proposed drugs may have positive effects." (PMID 39132498, 2024). "Our report also shows a reduced level of CAT in the mammary tumor control group (MTC), which may be attributed to the exploitation of antioxidant enzymes in the elimination of H2O2 via injection of LA7 cancer cells." (PMID 37373429, 2023). "It has been shown that concentration of total protein, urea, uric acid (UA), the total content of α-amino acids and lipid peroxidation products, and the activity of metabolic and antioxidant enzymes (in particular catalase) of saliva changed significantly in breast cancer." (PMID 35877435, 2022). "Increased NO levels and lower catalase levels in breast cancer patients indicate oxidativestress." (PMID 37701507, 2022). "It has been shown that concentration of total protein, urea, uric acid (UA), the total content of α-amino acids and lipid peroxidation products, and the activity of metabolic and antioxidant enzymes (in particular catalase—CAT) of saliva changed significantly in breast cancer." (PMID 35208240, 2022). "Interestingly, CAT overexpression in MCF-7 human breast cancer cells impaired cell proliferation and sensitized the cells to paclitaxel, etoposide, and arsenic trioxide." (PMID 34943091, 2021). "Treatment with vitamin E attenuated estrogen-induced nitrosative and oxidative stress in both in vivo and in vitro breast cancer models, while it enhanced expression of antioxidant enzymes such as superoxide dismutase, glutathione peroxidase, and catalase via upregulation of Nrf2." (PMID 32708855, 2020). "Researchers showed the attenuated activities of SOD, CAT, and GPx in mammary carcinomas." (PMID 33178325, 2020). "Additionally, catalase activity was significantly downregulated in MET-untreated co-cultures of MOs with breast cancer cells than in MET-untreated MOs cultured alone (p < 0.05)." (PMID 33108409, 2020). "Catalase in breast cancer cells is characterized by high activity and expression level." (PMID 32397133, 2020). "To this end, we overexpressed human catalase in MCF-7 breast cancer cells." (PMID 29535798, 2018). "Finally, since gene transcription is also regulated by chromatin modulation due to histone acetylation or DNA methylation, these epigenetic marks were also investigated as potential modulators of altered catalase expression in breast cancer cells." (PMID 29535798, 2018). "In addition, we demonstrated the important roles of RARα and JunB transcription factors in remodeling the chromatin and controlling catalase expression in breast cancer cells." (PMID 29467594, 2018). "The aim of this work was to study a potential link between ATO and catalase expression and the functional consequences of such putative relationship in mammary cancer cells exposed to ascorbate/menadione (Asc/Men), a H2O2-generating system widely used to induce oxidative stress." (PMID 29467594, 2018).
breast carcinoma (continued). "However, an increase in catalase levels has been reported in breast cancer tissue, malignant mesothelioma, and colorectal carcinoma." (PMID 27418953, 2016). "Moreover, addition of PEGylated catalase significantly protected breast cancer cell lines from ß-lap-induced lethality." (PMID 26462257, 2015). "Acrolein and phosphoramide mustard are the metabolites of cyclophosphamide that are among the causative agents, which reduce the activity of SOD, CAT, GPX, glutathione-S-transferase, and glucose-6-phosphate dehydrogenase in erythrocytes of CMF treated breast cancer patients." (PMID 26576218, 2015). "Given that catalase induces apoptosis in MCF7 breast cancer cells and that galectin-3 has an anti apoptotic role it is possible that that the up-regulation of galectin-3 is a cell survival mechanism against the catalase-induced apoptosis." (PMID 26222311, 2015). "Over-expressed catalase to alleviate mitochondrial oxidative stress in a mouse animal model of breast cancer could reduce metastatic tumor burden by >12-fold." (PMID 23217164, 2012). "CAT activation is postulated to exert control on breast cancer progression." (PMID 23153283, 2012). "Catalase-silencing sensitizes BT-20 breast carcinoma cells to ascorbic acid mediated cell death." (PMID 22551313, 2012). "Whether mtH2O2 is involved in the breast cancer cell migration induced by subclinical doses of irradiation was tested using a mitochondria-targeted version of human catalase (mtCAT), which effectively blocked irradiation-induced mtH2O2 production by both cell lines." (PMID 38978126, 2024). "Indeed, higher ROS production and decreased superoxide dismutases (SODs) and CAT activities have been observed in breast cancer patients, which supports the oxidative stress hypothesis in carcinogenesis." (PMID 30674338, 2019). "Moreover, SOD1 and N-acetyl-L-cysteine failed to improve MCF-7 cells viability in the presence of Asc/TETA, while catalase significantly inhibited the cytotoxicity of Asc/TETA to breast cancer cells, strongly suggesting that the selective cytotoxicity of Asc/TETA to cancer cells is H2O2-dependent." (PMID 28280522, 2017). "In addition, to further study whether the disturbed expression pattern of SOD1 and CAT in breast cancer cell is related with cell viability, SOD1 and CAT were knocked down by shRNA, respectively." (PMID 28280522, 2017). "Indeed, activities of CAT have been reported to be lowered in breast cancer patients." (PMID 23153283, 2012). "In breast cancer cells lines, increased malignancy is associated with high levels of reactive oxygen species-producing superoxide dismutase activity, in combination with decreased levels of reactive oxygen species-detoxifying glutathione peroxidases and the H2O2-detoxifying enzyme catalase." (PMID 21042593, 2010). "The decrease in catalase and AOA before surgery was inversely proportional to the breast cancer stage." (PMID 41596237, 2026). "The content of lipid peroxidation products, catalase activity, total antioxidant activity (AOA) and total peroxidase activity (TPA) in saliva were analyzed before and after breast cancer surgery." (PMID 41596237, 2026). "Postoperatively, increases in catalase, AOA, and OPA activity were observed only in Lum B (+) breast cancer." (PMID 41596237, 2026). "Cell viability and angiogenesis decreased in ethyl acetate extract-treated breast cancer cells, whereas apoptosis/cell cycle arrest increased as a result of down-regulating Bcl-2 expression and up-regulating Bax, SOD, CAT, and caspase 3/8 expression." (PMID 40699792, 2025). "Before surgery, a decrease in the concentration of total protein, urea, α-amino acids, and the activity of catalase, GGT, and LDH in saliva was observed with increasing breast cancer stage." (PMID 41295279, 2025). "In a preclinical in vitro breast cancer model, PTX-induced bystander cancer cell killing was amplified by SOD and inhibited by catalase, indicating that the effect was mediated by H2O2." (PMID 40872550, 2025).
breast carcinoma (continued). "Next, we evaluated the levels of the antioxidant defense system, including CAT, SOD, GSH, NO, and lipid peroxidation, in PDOs derived from different breast cancer samples." (PMID 40821783, 2025). "In a previous study, octyl gallate and gallic acid inhibited breast cancer progression through activating the intrinsic apoptotic signaling pathway, coupled with the upregulation of antioxidant enzymes SOD and CAT." (PMID 41440040, 2025). "We have shown an increase in the activity of antioxidant defense enzymes (catalase, GGT), as well as the level of NO in saliva in breast cancer." (PMID 41295279, 2025). "In conclusion, our findings indicate that markers including ESR2, TOMM20, NFE2L2, and CAT not only play a role in mitochondrial oxidative stress but may also influence drug response and cancer recurrence, making them promising biomarkers to predict prognosis in luminal breast cancer." (PMID 39767718, 2024). "Serum antioxidants catalase activity and the level of TAS weresignificantly diminished in breast carcinoma patients before treatment as compared to normal control." (PMID 37701507, 2022). "We showed that in breast cancer cells, vactosertib effectively inhibited the increased ROS level by GOX, similar to the effect of Catalase, a potent ROS scavenger." (PMID 36167880, 2022). "For luminal B (−) breast cancer, ALP and GGT activities reached maximum values, while LDH and catalase activities remained practically unchanged." (PMID 35877435, 2022). "In fact, leptin has been found to upregulate antioxidant enzymes such as superoxide dismutase (SOD), catalase (CAT), and heme-oxygenase 1 (HO-1), but decreased lipid peroxidase in colorectal and breast cancer cells." (PMID 33535537, 2021). "The NQO1:CAT ratios are suggested to be a therapeutic window in NSCLC, pancreatic and breast cancers." (PMID 34676172, 2021). "Treatment with the ruthenium-fluvastatin complex substantially improved the production of SOD, CAT, and GSH in breast cancer, possibly through enabling ROS to induce apoptotic events." (PMID 34221232, 2021). "In this regard, other studies have shown that the expression of CAT and SOD enzymes in breast cancer cells is reduced." (PMID 33976938, 2021). "In our investigation, we observed that ACE increased breast tissue CAT,GPx, and SOD enzymes in DMBA-induced breast cancer." (PMID 31826147, 2019). "Breast cancer is characterized by overexpression of superoxide dismutase (SOD) and downregulation of catalase and more resistance to hydrogen peroxide (H2O2) than normal cells." (PMID 28280522, 2017). "In contrast, previous analysis in plasma, erythrocytes, and whole blood of women with breast cancer showed decreased SOD, CAT, and GPx activity, being therefore insufficient for antioxidant protection." (PMID 29264992, 2017). "Given that one of the typical characteristics of breast cancer is SOD overexpression, along with compromised CAT expression, the intracellular oxidative stress is higher in the cancer cells compared to normal cells." (PMID 28280522, 2017). "Further, mimetic of catalase, EUK 134 was reported to attenuate viability, proliferation, clonal expansion, adhesion, and migration of breast cancer cells, in vitro." (PMID 28678839, 2017). "FoxM1 downregulates ROS levels by stimulating expression of ROS scavenger genes, such as MnSOD, catalase and PRDX3; the Nrf2-Prx I axis is important in human lung-cancer, prostate-cancer, colon-cancer, and breast-cancer development." (PMID 27517622, 2016). "In our study, on treatment of the breast cancer cell lines with CE, the SOD ratio to CAT and GPx was increased in both cell lines, leading to accumulation of hydrogen peroxide." (PMID 26700476, 2015). "The major events in the mechanism of NO induced apoptosis such as activation of catalase, PP2A and dephosphorylation of phosphorylated FOXO1 were also observed in MCF7 breast cancer cells." (PMID 23950968, 2013).
breast carcinoma (continued). "Morin significantly attenuated oxidative stress and brought the decreased of SOD, CAT, and GPx activities and the increased levels of TBARS and hydroperoxides to near normal values in rats were having mammary carcinoma." (PMID 23384060, 2013). "Increase in catalase bioactivity, following DETA treatment was also observed in another breast cancer cell line, MCF7." (PMID 23950968, 2013). "In addition, the CAT-MPO combination may greatly decrease the hazard of death from breast cancer." (PMID 22427832, 2012). "Attenuation of apoptosis by ectopic expression of catalase and superoxide dismutase reinforces the notion that ROS provide initial signal for BITC-induced apoptosis at least in breast cancer cells." (PMID 22359675, 2012). "After breast cancer surgery, catalase, AOA, and TPA activities increased, with catalase activity (+10.2%) and AOA (+34.7%) being higher at stage III, while the maximum increase in TPA was observed at stage I breast cancer (+118.9%, p = 0.0012)." (PMID 41596237, 2026). "Furthermore, P. vera L. leaves had a strong antioxidant impact on breast cancer cells by significantly raising levels of reduced glutathione (GSH), mammary glutathione peroxidase (GPx), SOD, and CAT." (PMID 40699792, 2025). "SOD activity was increased in all breast cancer subtypes, but the maximum increase in SOD activity was observed in the luminal B(+) subtype (+56.8%, p = 0.0099), which correlates with the maximum decrease in catalase activity in this subgroup." (PMID 40429927, 2025). "In the luminal A and luminal B(−) breast cancer subtypes, the activity of free SOD was close to the normal values, and the catalase activity was less suppressed compared with the luminal B(+) and non-luminal breast cancer subtypes." (PMID 40429927, 2025). "Similarly, CAT overexpression has been shown to inhibit cell proliferation in both smooth muscle and MCF-7 breast cancer models." (PMID 40647540, 2025). "Associations of polymorphisms in the hOGG1 (rs1052133), APEX1 (rs1130409), XPD (rs13181), SOD2 (rs4880), and CAT (rs1001179) genes were studied in 313 nonsmoking postmenopausal patients with luminal B subtype breast cancer." (PMID 39027127, 2024). "Finally, through in silico studies, we identified specific biomarkers, including TOMM20, NFE2L2, CAT, and ESR2, correlated with poor prognosis in luminal breast cancer." (PMID 39767718, 2024). "Within the breast cancer group, we showed the maximum differences for basal-like cancer in terms of increased levels of endogenous toxins (MM 254 and 280) and lipid peroxidation products (DC, MDA), as well as SOD/Catalase." (PMID 35877435, 2022). "The serum level of CAT was 369 ± 38.57 and 271.5 ± 51.43 in patients with breast cancer and controls, respectively, without statistically significant differences between them (p value = 0.062)." (PMID 36225290, 2022). "The ROS scavenger NAC or catalase did not suppress plasma-induced cell death in U373MG glioma or MDA-MB-231 breast cancer cells." (PMID 34074016, 2021). "Importantly, altered CAT expression has been correlated with resistance to therapy in GBM, pancreatic cancer, and breast cancer cells." (PMID 34943091, 2021). "Reducing expression of antiapoptotic regulators such as cIAP 1, Bcl-2, catalase,clusterin, HO-1, livin, XIAP, HSP27 and claspin was also demonstrated in human breast cancer line; the latter in support of mithochondrial apoptotic pathway using bromelain-based CHCT." (PMID 34466585, 2020). "Rajneeshet al., (2008) carried out the study on 40 newly diagnosed breast cancer patients and 100 healthy control subjects found significantly increased levels of glutathione (GSH), SOD, CAT, GPx concentrations and GST activities in breast cancer patients when compared to the control group." (PMID 32102525, 2020). "As expected, knockdown of CAT significantly recovered the ROS generation and enhanced migration and invasion, colony formation in low dose irradiation treated KRAS overexpressed breast cancer cells." (PMID 26515758, 2015).